EDNRB (endothelin receptor type B)
Diseases named in the same sentence as EDNRB in open-access papers (continued):
Sharing a sentence is not in itself a finding about the gene and the disease.
cancer (continued). "Previous research has elucidated the crucial inhibitory role of EDNRB in other cancer types." (PMID 38205153, 2024). "We next determined whether the combination of macitentan 45 mg/kg and EDNRB re-expression could inhibit cancer growth." (PMID 33257729, 2020). "We first determined whether our treatment strategy of inhibiting ETAR with macitentan and re-expressing EDNRB (the gene for ETBR) could effectively block cancer invasion in vitro and in a preclinical model of oral SCC." (PMID 33257729, 2020). "In addition, three common signature genes in the pathways concerning cancer were endothelin receptor B (EDNRB), hedgehog-interacting protein (HHIP), and MMP1." (PMID 33046043, 2020). "In contrast, the effects of ET3 and its selective binding to EDNRB on endothelin signaling and cancer progression may be dependent on cancer type." (PMID 32201539, 2020). "Re-expression of EDNRB on cancer cells produces antinociception via endogenous opioid secretion." (PMID 33257729, 2020). "In addition, several of the promoter-hypermethylated genes were associated with the development of human cancers and these include GIPC2, DIRAS3, TYSPL6, EDNRB, FYN, GDNF, RASSF1, and RASSF2." (PMID 21962230, 2011). "We next asked whether EDNRB isoforms might also regulate AKT activation in other cancers." (PMID 32201539, 2020). "Our analysis revealed 9 shared genes, with UBE2C, POLQ, RAD51, and HOXB7 being up-regulated and EDNRB, GPD1L, F10, SORBS2, and CXCL12 down-regulated in both cancers." (PMID 41790655, 2026). "Among the four selected candidate genes, DCC, PTGDR1, EDNRB, and ECAD, the promoter regions of all genes except PTGDR1 showed significantly higher methylation values in cancer areas than in normal mucosa areas." (PMID 38538728, 2024). "ETs regulate several processes in cancer, including cell survival and cell invasion through the binding to distinct G protein-coupled receptors (GPCR): ETAR (EDNRA), and ETBR (EDNRB)." (PMID 35406721, 2022). "On the other hand, the upregulated genes, such as GNG12, GNG4, WNT9A, EDNRB, FGF18, LAMA3, MMP2, etc., were found in pathways in cancer." (PMID 36239109, 2022). "These experiments revealed very low levels of EDNRB mRNA in the normal mammary cells (HMEC) and the ZR75 cancer cell line; the highest EDNRB expression was detected in MCF-7 cells, followed by MDA-MB-231 and BT-549 cell lines, respectively." (PMID 32201539, 2020). "The genes that were shared by three different cancers (i.e., FGFR3, EPAS1, SRC, and FOXD3) are shown in coral, and the genes that were shared by two types of cancers (i.e., PPARG, FOXO1, CDK4, NKX3-1, PIK3R1, PRKCB and EDNRB) are shown in light pink." (PMID 28178311, 2017). "From the differential genes involved in these pathways, we identified several gene clusters uniquely upregulated in the CAFWPOI 4-5 type; neuronal development and function-related (RELN, MYH10, CACNB4, OXTR, CAV3, CHRM2) and inflammation and cancer-related (RELN, IL21R, EDNRB, CAV3, OXTR)." (PMID 36045118, 2022). "EDNRB and MITF also belong to the “pathways in cancer” pathway." (PMID 34722301, 2021). "Furthermore, three DEGs (FCER1A, EDNRB, and TGFBI) in the model of relapse showed prognostic significance for predicting the survival of patients with cancer through Cox proportional hazards regression model-based survival analysis." (PMID 33138797, 2020). "Ki67 staining was positive in all four treatment groups, indicating that macitentan and EDNRB re-expression did not significantly inhibit cancer proliferation." (PMID 33257729, 2020). "In addition to EDNRB and WARS, the remaining 19 genes showing evidence interacting in the progress of various types of cancer, but left few traces showing the connection with UM prognosis in the previous research." (PMID 33196683, 2020).
cancer (continued). "The identified membrane proteins serve as receptors (EPHB6, ACKR1, and EDNRB) or adhesion molecules (EPCAM) and may enhance antitumor immunity (TENM2 and CLEC‐10A); thus, they may contribute to enhanced mEHT‐induced cancer destruction through regulating the TME related immune response." (PMID 38217262, 2024). "Cluster 2 contains instead receptor-ligand axes that are more frequently concordantly downregulated in cancer subtypes, although several of these might still be concordantly upregulated in specific subtypes (e.g., CXCR2, EDNRB, FFPR2, or LGR6, GALR2, and UTS2R)." (PMID 38723607, 2024). "Interestingly, EDNRB-436 trended toward protection in this same cancer subtype and stage, though the difference was not significant." (PMID 32201539, 2020). "Significant differences between cancer and their surrounding non-cancerous tissues were observed in the methylation values of DCC (p = 0.003), EDNRB (p = 0.001), and ECAD (p = 0.043)." (PMID 38538728, 2024).
cardiovascular diseases (4 papers, 2015 to 2025). "Another biological function describrd cardiovascular disease gene as ABL2, ABL2 and EDNRB." (PMID 26345457, 2015).
neurological disease (3 papers, 2011 to 2024). "EDNRB expression is down-regulated in both ZIKV-infected mouse primary astrocytes and U251 astrocytes, revealing a potential malfunction associated with ZIKV-induced neurological diseases." (PMID 39600882, 2024).
respiratory disease (1 paper, 2011). "A subset of genes co-expressed with AQP4 and associated to respiratory disease were assigned to potential anti-tumorigenic function like CAV1, EDNRB, or SELENBP1, whereas genes more related to pro-tumorigenic function like CDK2, FOXM1, PLK1 or RRM1 were found to be anti-correlated with AQP4." (PMID 21548930, 2011).
EDNRB also shares sentences with these, for which no sentence is quoted: Cerebral ischemia (11 papers); pulmonary hypertension (8); endothelial dysfunction (7); coronary artery disease (5); heart failure (5); infection (5); ischemia (5); megacolon (5); Stroke (5); systemic sclerosis (4); triple-negative breast carcinoma (4); chronic heart failure (3); Down syndrome (3); liver cancer (3); myocarditis (3); nasopharyngeal carcinoma (3); preeclampsia (3); Sepsis (3); skin cancer (3); subarachnoid hemorrhage (3); Waardenburg syndrome type 4A (3); astrocytoma (2); autoimmune myocarditis (2); bladder cancer (2); Cirrhosis (2); congenital heart disease (2); Depression (2); esophageal SCC (2); essential hypertension (2); infarction (2).
A further 94 diseases each share a sentence with EDNRB in 2 papers or fewer.